PRRX2 (paired related homeobox 2)
Description:
May play a role in the scarless healing of cutaneous wounds during the first two trimesters of development.
Synonyms: PMX2; PRX2
Tractability: No criterion of Open Targets' tractability assessment is met for any kind of drug.
Gene: Protein-coding gene on chromosome 9 (129,665,630 to 129,722,674, forward strand). Ensembl gene ENSG00000167157.
Subcellular location: Nucleus
Subcellular location (Human Protein Atlas): Nucleoplasm; Nuclear bodies
Gene Ontology:
Molecular function: sequence-specific double-stranded DNA binding; DNA-binding transcription factor activity; DNA-binding transcription factor activity, RNA polymerase II-specific; RNA polymerase II cis-regulatory region sequence-specific DNA binding; DNA binding
Biological process: regulation of DNA-templated transcription; regulation of transcription by RNA polymerase II
Cellular component: chromatin; nucleus
Genetic constraint (gnomAD): Loss-of-function variants: 10 observed, 14.57 expected, observed/expected ratio (o/e) 0.69, 90% interval 0.42 to 1.16. The upper end of that interval is the gene's LOEUF score, 1.16, which puts it in group 5 of 6, group 1 being the genes least tolerant of losing a copy. Missense variants: 251 observed, 239.43 expected, observed/expected ratio (o/e) 1.05, 90% interval 0.94 to 1.16. Synonymous variants: 119 observed, 100.25 expected, observed/expected ratio (o/e) 1.19, 90% interval 1.02 to 1.38.
Homologues: Orthologues: chimpanzee PRRX2 (100% identical), macaque PRRX2 (100% identical), dog PRRX2 (95% identical), pig PRRX2 (95% identical), rat Prrx2 (89% identical), mouse Prrx2 (88% identical), guinea pig PRRX2 (73% identical), rabbit PRRX2 (63% identical). Paralogues in human: PRRX1 (59% identical), ARX (33% identical), ALX4 (32% identical), RAX (32% identical), SHOX2 (29% identical), SHOX (28% identical), PITX1 (28% identical), ALX1 (28% identical), PHOX2B (28% identical), PITX2 (28% identical), VSX2 (28% identical), ALX3 (27% identical), and 38 more.
Diseases named in the same sentence as PRRX2 in open-access papers:
PRRX2 is named in the same sentence as 27 diseases in open-access papers, as found by Europe PMC text mining. Sharing a sentence is not in itself a finding about the gene and the disease. The quoted sentences say what the papers report.
glioblastoma (7 papers, 2022 to 2025). The most malignant astrocytic tumor (WHO grade IV). "PRRX2 has also been implicated in the progression of glioblastoma through its regulation of ferroptosis." (PMID 39434056, 2024). "Contrasting with these oncogenic circRNAs, circLRFN5 exhibits tumor-suppressive properties in glioblastoma (GBM) by promoting ubiquitin-mediated degradation of PRRX2, a transcriptional activator of GCH1." (PMID 40403492, 2025). "Yang Jiang and colleagues demonstrated that circLRFN5 can facilitate ferroptosis by binding to PRRX2 protein and inducing its degradation, thereby inhibiting the growth of glioblastoma." (PMID 39493751, 2024). "For example, circLRFN5 is expected to be combined with alkalinization therapy because Prrx2 expression was highly induced by acidic pHe in this study and PRRX2 had inhibitory activity of ferroptosis in glioblastoma." (PMID 39372863, 2024). "Overexpressing CircLRFN5 in glioblastoma has been demonstrated to mediate paired related homeobox 2 (PRRX2) protein degradation via the ubiquitin-proteasomal pathway, which transcriptionally downregulates GCH1-BH4 in GSCs and provokes ferroptosis." (PMID 39309434, 2024). "Furthermore, our previous study showed that circLRFN5 inhibits the progression of glioblastoma through the PRRX2/GCH1-mediated ferroptosis." (PMID 37723588, 2023). "Previous research has demonstrated that PRRX2 functions as a transcription factor and may exert transcriptional regulatory effects on GCH1, which plays a crucial role in mediating ferroptosis in glioblastoma." (PMID 39434056, 2024).
breast carcinoma (6 papers, 2022 to 2025). "In the level of SPE of PRRX2, the survival rate of patients is significantly different (P < 0.05; log-rank test), demonstrating that stMGATF can identify hub upstream TFs closely associated with good prognosis in breast cancer patients through SDGs." (PMID 37736108, 2023). "Among these 4 upstream TFs, PRRX2, TWIST1, and PRRX1 were reported to induce mesenchymal–epithelial cell transformation and were associated with breast cancer metastasis." (PMID 37736108, 2023). "PRRX2 enhances invasion and migration in mammary epithelial cells and correlates with poor prognosis in breast cancer via activating TGF-β." (PMID 36266731, 2022). "PRRX2 eRNA and mRNA expression levels are correlated, and targeting the PRRX2 eRNA to its cognate enhancer promotes breast cancer cell proliferation, an effect that is abrogated upon depletion of BCAS2." (PMID 36039999, 2022). "Over-expression of PRRX2 induces epithelial to mesenchymal transition (EMT) in breast carcinoma and enhances migration and invasiveness in breast cancer." (PMID 37887568, 2023).
glioma (6 papers, 2022 to 2026). A benign or malignant brain and spinal cord tumor that arises from glial cells (astrocytes, oligodendrocytes, ependymal cells). "All the qPCR, western blotting and immunohistochemistry assays confirmed PRRX2 expressed higher in glioma and GBM tissues than the NBT and even higher with increasing WHO grades, and the highest expression was found in GBM." (PMID 36266731, 2022). "CircLRFN5 can mediate paired related homeobox 2 (PRRX2) via the ubiquitin proteasome pathway, and in gliomas, PRRX2 activates transcriptional upregulation of GTP cyclohydrolase 1 (GCH1) expression, a substance that inhibits ferroptosis by producing the antioxidant tetrahydrobiopterin (BH4)." (PMID 37152286, 2023). "Conversely, circLRFN5 overexpression reduces glioma CSC viability, proliferation, and tumorigenicity by inducing PRRX2/GCH1 - mediated ferroptosis." (PMID 41601687, 2026). "CircLRFN5 interacts with PRRX2 and promotes its ubiquitination and proteasomal degradation, transcriptionally reducing PRRX2-mediated GCH1 expression, resulting in the induction of ferroptosis in glioma." (PMID 37686142, 2023). "CircLRFN5 binds to the paired related homeobox 2 (PRRX2) protein and promotes its ubiquitin-mediated degradation, thereby transcriptionally upregulating the expression of the ferroptosis suppressor GCH1 in glioma stem cells (GSCs), leading to ferroptosis induction." (PMID 38072908, 2023).
colon cancer (4 papers, 2021 to 2024). "PRRX2 was also reported to promote colon cancer liver metastasis via activation of Wnt/β-catenin signaling." (PMID 36266731, 2022). "PRRX2 was reported as an oncogene in several cancers, including hepatocellular carcinoma, prostate cancer, and colon cancer." (PMID 36266731, 2022). "PRRX2, a member of the paired family of homeobox proteins that mediates epithelial to mesenchymal transition (EMT) and metastasis in breast and colon cancer." (PMID 39434056, 2024).
prostate carcinoma (3 papers, 2017 to 2024). A carcinoma that arises from epithelial cells of the prostate gland. "PRRX2 expression was upregulated in prostate cancer and acted as a regulator of enzalutamide resistance." (PMID 36266731, 2022). "Moreover, 8 of these TFs (FOXJ2, GATA6, NFE2L1, NFIL3, PRRX2, TEF, EBF2 and ZBTB18) were found to be differentially expressed in this study making them not only candidate biomarkers of prostate cancer but also potential therapeutic targets." (PMID 28380430, 2017).
myocardial infarction (2 papers, 2020 to 2025). Gross necrosis of the myocardium, as a result of interruption of the blood supply to the area, as in coronary thrombosis. "PRRX2 is highly expressed in choroidal fibroblasts, and an upregulation of PRRX2 in (cardiac mice) fibroblasts was described after myocardial infarction." (PMID 32789304, 2020).
osteoporosis (2 papers, 2023 to 2024). A condition of reduced bone mass, with decreased cortical thickness and a decrease in the number and size of the trabeculae of cancellous bone (but normal chemical composition), resulting in increased fracture incidence. "Finally, myoblast-derived exosomal Prrx2 alleviated osteoporosis in mice via up-regulating MIR22HG and activating the Hippo pathway." (PMID 37081396, 2023). "In this study, up-regulation of Prrx2 in the exosomes derived from myoblasts contributed to BMSC osteogenic differentiation in vitro and restrained OVX-induced osteoporosis in mice in vivo." (PMID 37081396, 2023). "In the present work, we verified our hypothesis and found that Prrx2 was up-regulated in the myoblast-derived exosomes, which facilitated BMSC osteogenic differentiation and relieved osteoporosis." (PMID 37081396, 2023). "However, whether exosomal Prrx2 from C2C12 myoblasts can promote osteogenic differentiation and alleviate osteoporosis remains unclear, which deserves further investigation." (PMID 37081396, 2023).
triple-negative breast carcinoma (2 papers, 2021). An invasive breast carcinoma which is negative for expression of estrogen receptor (ER), progesterone receptor (PR), and human epidermal growth factor receptor 2 (HER2). "MiR-212-5p represses EMT in triple-negative breast cancer by targeting paired related homeobox 2 (PRRX2)." (PMID 33934686, 2021). "For example, miR-212-5p overexpression inhibits cell migration and invasion of triple-negative breast cancer cells in vitro by downregulating paired related homeobox 2 (Prrx2) expression." (PMID 33760887, 2021).
atherosclerosis (1 paper, 2025). A disease characterized by the build-up of fatty material and calcium deposition in the arterial wall resulting in partial or complete occlusion of the arterial lumen. "Of the 25 shared novel atherosclerosis loci with evidence of colocalization, 7 analyses strongly colocalized with PRPA ≥0.80 (nearest gene: BNC2, SCAI, TSC22D2, SRRM1, ABCB11, PRRX2)." (PMID 40313769, 2025).
congenital heart defects (1 paper, 2021). "Moreover, SEMA3A and PRRX2 mutations also lead to congenital heart defects." (PMID 34895303, 2021).
heart failure (1 paper, 2020). Inability of the heart to pump blood at an adequate rate to meet tissue metabolic requirements. "While in the MI model of mice with Prrx2 knockdown, 16% of mice died of cardiac rupture and 8% mice died of heart failure." (PMID 31880857, 2020).
infarction (1 paper, 2020). A localised pathological necrosis of tissue resulting from obstruction of the blood supply usually by a thrombus, an embolus, or vascular torsion. "Adenovirus‐mediated gene knock down of Prrx2 increased survival rate, alleviated cardiac fibrosis, decreased infarction sizes and improved cardiac functions in mice with MI." (PMID 31880857, 2020).
melanoma (1 paper, 2024). A malignant, usually aggressive tumor composed of atypical, neoplastic melanocytes. "Ectopic WT-Bmal1 and dHLH-Bmal1 increased genes associated with mesenchymal melanoma state, such as Sox9, Fn1, Col1a1, Prrx2, Klf4, Snai2, Twist2, Lmo1 and Axl31." (PMID 38245503, 2024).
Myocardial fibrosis (1 paper, 2020). "The aim of this study is to investigate whether the transcriptional factor paired‐related homeobox 2 (Prrx2) regulates Wnt5a gene expression and the role in myocardial fibrosis following MI." (PMID 31880857, 2020).
Stroke (1 paper, 2020). Sudden impairment of blood flow to a part of the brain due to occlusion or rupture of an artery to the brain. "In perspective, Prrx2 or Wnt5a inhibitor maybe a new drug to treat ischaemia‐related cardiovascular diseases, such as acute MI and stroke." (PMID 31880857, 2020).
cancer (11 papers, 2018 to 2025). A tumor composed of atypical neoplastic, often pleomorphic cells that invade other tissues. "Inhibition of PRRX2 was previously correlated with lower expression of genes controlling epithelial-mesenchymal transition, a process linked to cancer progression, specially through inactivation of Wnt/β-catenin pathway — a hallmark of ACP." (PMID 40575267, 2025). "Among these candidates, PRRX2 captured our attention because it is overexpressed in highly invasive and metastatic malignant tumors." (PMID 34350181, 2021). "Two of these markers, NOBOX and PRRX2 show no representation in the literature in association with this cancer type." (PMID 38886487, 2024). "In consequence, we hypothesize that the rs181747 CC genotype affects the binding of PRRX2 to IL-6 and that the generated IL-6 contributes to cancer development and progression via p-STAT3 and facilitates chemotactic movement of immune cells." (PMID 37035153, 2023). "Other candidates, such as PRRX2 and CST3, confer metastatic properties to cancer cells through the TGF-β pathway." (PMID 30102725, 2018). "Moreover, QSOX2 silencing in NSCLC cell lines resulted in inhibition of cancer cell proliferation, induction of apoptosis, and decreased expression of cell division-related genes (CENPF and NUSAP1) and Wnt pathway activators (PRRX2 and Nuc-β-catenin)." (PMID 34350181, 2021).
tumor (5 papers, 2022 to 2024). "The tumor volumes and sizes were obviously decreased after circLRFN5 overexpression, while they increased after PRRX2 overexpression or GCH1 overexpression, respectively." (PMID 36266731, 2022). "Higher expression of PRRX2 in primary samples may help tumor metastasis since inhibition of PRRX2 has been shown to suppress liver metastasis." (PMID 37887568, 2023).
ischaemic heart diseases (1 paper, 2020). "In conclusions, targeting Prrx2‐Wnt5a signalling should be considered to improve cardiac remodelling in patients with ischaemic heart diseases." (PMID 31880857, 2020). "Clinically, inhibition of Prrx2 or Wnt5a is an effective approach to improve cardiac remodelling in patients with ischaemic heart diseases." (PMID 31880857, 2020).
PRRX2 also shares sentences with these, for which no sentence is quoted: hepatocellular carcinoma (2 papers); adenocarcinoma of the lung (1); alcoholic hepatitis (1); cardiovascular diseases (1); craniosynostosis (1); fibrosis (1); ischemic stroke (1); mesothelioma (1); polydactyly (1).